TNF (tumor necrosis factor)
Diseases named in the same sentence as TNF in open-access papers (continued):
Sharing a sentence is not in itself a finding about the gene and the disease.
diabetes (continued). "O2− production derived from Nox is enhanced by several pathophysiological conditions such as tumor necrosis factor (TNFα) expression, integrin ligation, diabetes, or oxidized LDL." (PMID 35055099, 2022). "For instance, the overexpression of tumor necrosis factor-alpha (TNF-α) and interleukins (IL) cytokines, that play major roles in metabolic pathways, can promote the pathogenesis of diabetes." (PMID 36497992, 2022). "With the progression of the disease, the mRNA expression levels of IL-6, ICAM, and TNF-α were in a high expression state in the diabetes group, and a new peak appeared at the 10th week." (PMID 35126785, 2022). "Diabetes-enhanced inflammation has a dramatic effect on gene expression in the gingiva as shown by mRNA profiling in animals treated with a TNF inhibitor." (PMID 36304447, 2022). "From the literature evidence, it has been found that the levels of TNF- α significantly increase in animal model of diabetes administered with STZ." (PMID 36091594, 2022). "In response to injury, M1 phenotype macrophages release IL-6 and TNF-α, and in Type 2 diabetes mellitus, levels of these cytokines are elevated." (PMID 33628374, 2021). "TNF-α is one of the pro-inflammatory cytokines synthesized by adipose tissue, and high TNF-α levels are one of the critical risk factors for diabetes." (PMID 33435383, 2021). "It has been demonstrated that chronic inflammation is associated with T2DM, and certain proinflammatory cytokines like TNF-α are involved in the development of insulin resistance, leading to diabetes." (PMID 33671490, 2021). "MMP2 gene expression was unaffected by either concentration of TNF-α, or the presence of diabetes (ND-DF n = 5, T2DM-DF n = 4) and this was mirrored at the protein level (n = 4)." (PMID 33446687, 2021). "They found that the average TNF-α saliva values were in the order of periodontal disease patients with diabetes > periodontal disease patients who smoked > periodontal disease patient > healthy subjects." (PMID 34199256, 2021). "Our results revealed that TNF-α and IL-6, and NF-κB were elevated in the T2D myocardium, which confirms the involvement of inflammation in the pathogenesis of diabetes-induced cardiac injury." (PMID 34497520, 2021). "TNF-α secretion increases dramatically in both obese subjects and patients with diabetes, and it directly contributes to the reduction of adiponectin." (PMID 34257685, 2021). "A significant (p < 0.05) upregulation of hepatic TNF-α and IL-6 expression and downregulation (p < 0.05) of Nrf-2 expression were observed during diabetes onset." (PMID 34956587, 2021). "In a diabetes animal model, the proinflammatory cytokines IL-6, TNF-α, and IL-1β increased significantly in rat pancreatic tissue." (PMID 33774704, 2021). "Immune markers linking CP and diabetes have also been reported in relation to glycation dynamics and TNF-α, which have been argued to constitute reliable biomarkers of inflammation in gingival crevicular fluid and serum." (PMID 34776994, 2021). "Higher levels of TNF-alpha, IL-1beta, and IL-6 were found in the serum of type 2 diabetes mellitus compared with healthy control, which correlate with the development and progression of DR." (PMID 34699316, 2021). "In contrast, tumor necrosis factor (TNF)-α has been found to be upregulated in obese patients and those suffering from diabetes and is known to directly contribute to reduced adiponectin expression." (PMID 34257685, 2021). "High glucose and AGEs promote macrophages to M1 polarization and the release of inflammatory cytokines, such as tumor necrosis factor (TNF), contributing to pathogenesis in the early stage of diabetes." (PMID 34025445, 2021). "One study evaluated the proinflammatory cytokine levels (TNF-α, IL-6) in left ventricular diastolic dysfunction (LVDD), the earliest manifestation of diabetes-induced left ventricular dysfunction, and the result was increased plasma levels of IL-6 and TNF-α." (PMID 34506248, 2021).
diabetes (continued). "For example, diabetes, a prevalent comorbidity in our study, is characterized by an exaggerated pro-inflammatory cytokine response, notably interleukin-1 (IL), IL-6, and tumor necrosis factor (TNF)-α." (PMID 34872493, 2021). "TNF-α production in the liver is crucial in the pathogenesis of diabetes and non-alcoholic steatohepatitis (NASH)." (PMID 34297734, 2021). "In rats with induced diabetes, there was, typically, increased expression of TNF-alpha and INF-gamma as well as increased ROS production." (PMID 33150520, 2021). "NF-κB, a transcription factor that controls numerous pro-inflammatory proteins production (including TNF-α, IL-6 and IL- 1β), has been recognized to be crucial in the development of diabetes and obesity-related diseases." (PMID 34571976, 2021). "Diabetes increased the mRNA expression of TNFα, IL1β, and IL-17 in peri-implant gingival tissues (DM vs. WT), and peri-implantitis further upregulated the expression levels of these pro-inflammatory proteins (DM+lig vs. DM)." (PMID 34401982, 2021). "Nevertheless, it was proven that serum TNF-α increases in response to prolonged inflammation related to arterial hypertension and diabetes (which were present in the vast majority of patients included in this study)." (PMID 34571700, 2021). "TNFα-μMT−/− mice delayed significantly the progression of diabetes compared to wild-type TNFα-μMT+/+ mice." (PMID 34778464, 2021). "Moreover, chronic inflammation associated with diabetes favors carcinogenesis, malignant transformation, tumor growth, invasion and metastasis through the action of proinflammatory cytokines, such as tumor necrosis factor-alpha (TNF-α) and interleukin-6 (Il-6)." (PMID 33922197, 2021). "Our results in mice are consistent with the study of a streptozotocin-induced diabetes rat model, wherein increased levels of the proinflammatory cytokines IL-6, TNF-α, and IL-1β were found in diabetic rat pancreatic tissue." (PMID 33774704, 2021). "Recent work further identified that CXCL13/CXCR5 contributes to diabetes-induced mechanical hypersensitivities by activating pERK, pSTAT3, and pAKT pathways and promoting TNF-α and IL-6 production in SCDH." (PMID 33602238, 2021). "A specific medical condition was documented in six individuals: Diabetes mellitus (n = 2); selective immunoglobulin A deficiency (n = 1); untreated HIV infection (n = 1); chronic hepatitis C (n = 1); and treatment by tumor necrosis factor inhibitors (n = 1)." (PMID 33805019, 2021). "Increased TNF-α expression has been shown to improve chronic wound healing and diabetes-induced skin repair disorders in diabetic rats." (PMID 34209306, 2021). "Induction of diabetes resulted in a significant (p < 0.05) increase in plasma and hepatic IL-6 (645.3 and 104.5%, respectively) and TNF-α (69.4 and 479.8%, respectively) concentrations when compared with normal rats." (PMID 34956587, 2021). "It has been revealed that most macrophages in the adipose tissue of diabetics are M1 macrophages, which play key functions during the pathological processes by secreting TNF-α and triggering chronic inflammation in these patients." (PMID 33746897, 2021). "These rats with STZ-induced diabetes were typically found to have increased TNF-alpha and interferon-gamma (INF-gamma) expression as well as increased ROS production." (PMID 33150520, 2021). "Another study showed that the levels of TNF-α in saliva were significantly increased in subjects with type 2 diabetes mellitus compared with healthy controls." (PMID 33676486, 2021). "We chose to use 1 ng/ml IL-1β empirically, because this concentration promoted elevated expression of TNFα, IL-1β, IL-6 and IL-8 in hMC cultures like that observed in the vitreous of diabetic patients and retina of experimental diabetes models." (PMID 33958662, 2021). "The expression of VEGFA, MCP‐1, TGF‐β1 and TNF‐α was increased in the diabetes, diabetes + hUSCs‐Exo control and diabetes + hUSCs‐Exo miR‐16‐5p groups compared with the normal group (all P < .05)." (PMID 31568645, 2021).
diabetes (continued). "The expressions of TNF‐α, the p‐NF‐κB p65/NF‐κB p65 ratio, and p‐IκBα/IκBα ratio were markedly increased in DM mice compared with normal mice (p < .05), which showed that diabetes significantly exacerbated the inflammatory stress in the hippocampus of mice." (PMID 34531993, 2021). "TNFα is directly involved in the destruction of β-cells in isolated islets and plays a key role in the onset of diabetes in mice through the regulation of dendritic cell maturation and activation of islet-specific pancreatic T-cells." (PMID 34572059, 2021). "AA, the precursor of LXA4 and PGE2, prevented streptozotocin (STZ)-induced type 1 and type 2 diabetes mellitus and suppressed plasma IL-6 and TNF-α levels and the pro-inflammatory gene NF-κB to the same extent as that of LXA4." (PMID 34944517, 2021). "The level of TNF- α was decreased with significant differences in statistical analysis between control and Diabetes groups (P=0.0102)." (PMID 34249265, 2021). "Diabetes is a proinflammatory process, and several cytokines including interleukin-1β (IL-1β), IL-18, and tumor necrosis factor-alpha (TNF-α) are highly expressed in DbCM." (PMID 35145423, 2021). "On the other hand, obesity as a general comorbidity with diabetes, improves the systemic chronic inflammation by affecting the both innate and adaptive immune systems as well as the level of IL-6 and even TNF-α." (PMID 33746897, 2021). "Individuals with diabetes have also been shown to elevate levels of the proinflammatory cytokine, especially IL-1, IL-6, and tumor necrosis factor-alpha (TNF-alpha), and different markerssuch as C reactive protein, D-dimer, and fibrinogen." (PMID 35540698, 2021). "The reverse was the case for hepatic IL-6 and TNF-α, as diabetes onset significantly (p < 0.05) increased the expression of these genes by 228.0 and 95.1%, respectively." (PMID 34956587, 2021). "Meanwhile, compared with the diabetes + hUSCs‐Exo control group, the expression of VEGFA, MCP‐1, TGF‐β1 and TNF‐α was reduced in the diabetes + hUSCs‐Exo miR‐16‐5p group (all P < .05), while elevated levels were detected in the diabetes group (all P < .05)." (PMID 31568645, 2021). "The LXR-enhanced phagolytic activity of resKCs and decreased TNF-α production by recMφs are both beneficial for host protection against bacterial infections and TNF-α-mediated metabolic disease (diabetes, atherosclerosis, NASH, etc.)." (PMID 34297734, 2021). "The levels of GFAP and the secretion of TNF-α, IL-1β, and IL-6 were significantly increased in the retinas of mice with diabetes compared with those of the mice in the normal group." (PMID 34938383, 2021). "In diabetes and obesity, increased levels of IL-6 and TNF-α have been demonstrated, whereas the serum levels of IL-6 and CRP have been shown to predict the future occurrence of diabetes mellitus type 2." (PMID 34452136, 2021). "Like AA, LXA4 prevented the development of alloxan- and streptozotocin-induced type 1 and type 2 diabetes mellitus, respectively, and suppressed IL-6 and TNF-α production and NF-kB expression." (PMID 34944517, 2021). "The presence of a chronic subclinical proinflammatory state has been well-described in the setting of diabetes mellitus as activation of IL-1β, TNF-α, and IL-6 signaling pathways often precedes the onset of diabetes mellitus." (PMID 33755703, 2021). "It was also reported that EIF4A3 can regulate cell cycle and apoptosis through TNF-α/NF-ĸB signaling pathway, which is one of the key signal pathways affecting diabetes." (PMID 35046894, 2021). "There was a reduced level of inflammatory mediators, IL-6 and TNFα, in both diabetes and non-diabetes patients while using metformin." (PMID 34441802, 2021). "In this sense, supplementation of 45 g/day of a high-amylose maize to pre-diabetes patients for 12 weeks resulted in significant decreases in the concentration of TNF-α." (PMID 34957184, 2021).
diabetes (continued). "Against the background of violation of the structural and functional organization of the islets of Langerhans in conditions of diabetes, an increase in the content of TNF-α in the pancreas was shown." (PMID 34572994, 2021). "For example, aortic gene expression of TNF-α was significantly upregulated after 10 weeks of diabetes, which was significantly attenuated by MCC95021." (PMID 34588488, 2021). "Diabetes significantly triggered the increases of pro-inflammatory cytokines (TNF-α and IL-6) and decrease of the anti-inflammatory cytokines (IL-10)." (PMID 34497508, 2021). "This cytokine profile is consistent with the one reported in the current study when primary MGCs are exposed to hyperglycemia and high TNFα, subsequently referred to as “diabetes-like” stress conditions." (PMID 34071438, 2021). "Estrogen has been found to suppress the production of inflammatory mediators, such as IL-1, IL-6 and TNF-α, and these parameters are reported to play a decisive role in the pathogenesis of diabetes mellitus." (PMID 34746187, 2021). "The rationale of choosing this biomarker as a leading factor for investigation among other candidates is that IL-6 and tumor necrosis factor-alpha (TNF-α) appear to have the highest impact on the promotion of CAD in patients with diabetes mellitus." (PMID 34193056, 2021). "Wang, Z found that the inflammatory response related proteins were significantly increased in the brain with diabetes, including tumor necrosis factor-α (TNF-α), NF-κB, cyclooxygenase-2 (Cox-2) and interleukin-6 (IL-6)." (PMID 33602334, 2021). "In a rat model of diabetes, mangiferin has been shown to promote wound healing caused by diabetes by upregulating the expression of Nrf2, VEGF, and PI3K and downregulating the expression of TNFα and NF-κB p65." (PMID 33671866, 2021). "Our results showed that vitamin D3 significantly inhibited the protein expression level of TNF‐α, suggesting that vitamin D3 exerted anti‐inflammatory effects on diabetes‐induced cognitive impairment." (PMID 34531993, 2021). "Chronic and progressive inflammation indicated by elevated hippocampal IL‐1β and TNF‐α expression is known to play a role in diabetes‐related dementia." (PMID 33346402, 2021). "Consistent odds were observed for stroke while controlling for different combinations of uncontrolled diabetes, TNFα and IL6." (PMID 33510184, 2021). "The objective of the present study was to identify the association of the TNF-α- 308G/A and leptin receptor (LEPR) Gln223Arg polymorphisms with the risk of development of type 2 diabetes mellitus (T2DM)." (PMID 35052401, 2021). "In animals from the control group and rats with diabetes, who were administrated with Galega officinalis extract, a decrease in the content of TNF-α was demonstrated in the pancreas by 40 and 37%, respectively." (PMID 34572994, 2021). "The Nrf2 activator dh404 prevented an increase in diabetes-induced inflammatory mediators, including TNF-α, IL-6, ICAM-1, and MCP-1, in Müller cells." (PMID 34938383, 2021). "In diabetic patients with dyslipidemia, pro-inflammatory cytokines such as TNF-α and interleukins are progressively elevated as diabetes or dyslipidemia worsens." (PMID 33828528, 2021). "The observed increase in the concentration of these inflammatory mediators (IL-6 and TNF-α) after diabetes induction in rats was suppressed by TCA treatment, suggesting the anti-inflammatory effect of TCA in diabetic rats." (PMID 34956587, 2021). "As an inflammatory microenvironment, diabetes is characterized by 2-3-fold elevated concentrations of tumor necrosis factor (TNF), IL-6 and C-reactive protein (CRP) in the peripheral blood." (PMID 34975496, 2021). "Changes in diabetes-related inflammatory status were measured in terms of IL-6, TNF-α, and IL-1β levels in the serum and phospho NFκB-p65 protein expression." (PMID 34439476, 2021).
diabetes (continued). "Cytokines, such as TNF-α, have been shown to change based on age, infection, or other system conditions including hypertension and diabetes." (PMID 35052396, 2021). "The findings suggest that those CD106-positive HSCs expressing TNF-α exhibited phenotypic change and therefore are a candidate for diabetes-specific stem cells." (PMID 33990693, 2021). "TNF-α registered a statistically significant decrease only in the diabetes group after dental extraction, together with a decrement of mean HbA1c levels in the diabetes group." (PMID 34829612, 2021). "The odds for heart attack among those with diabetes, increased by 20 fold in presence of high levels of triglycerides, TNFα, and IL6 when coupled with low levels of high-density lipid cholesterol (HDL-C)." (PMID 33510184, 2021). "Serum levels of apelin and TNF-α were higher in patients with diabetes than those in the NC group, as well as in the DPN group as compared to the non-DPN group; furthermore, some NCV values were significantly reduced in the DPN group." (PMID 33907154, 2021). "The competitive interference ability of sTNFSF12 in TNFα signaling in adipocytes was revealed—sTNFSF12 acted as a protective element in type 2 diabetes mellitus (T2DM)." (PMID 34572446, 2021). "Previously, we have demonstrated that diabetes increases intestinal iNOS expression, NO levels in the portal vein, IL-1β and TNF-α expression of Kupffer cells in the liver." (PMID 34043673, 2021). "We show that plasma levels of TNFα and IL-1β are increased early, and persist from 4 weeks of diabetes." (PMID 32153425, 2020). "Scientific evidence also suggests the inflammatory factors, tumor necrosis factor-α (TNF-α) and interleukin-6 (IL-6), are well known to be associated with the development of renal disease in diabetes." (PMID 32076626, 2020). "Previous investigations have shown that in diabetes mellitus the production of inflammatory cytokines including IL-1, IL-6 and TNF-α increase." (PMID 32817750, 2020). "Vascular calcification derived from atherosclerosis and diabetes has been demonstrated to be a chronic inflammation event, which is regulated by inflammatory cytokines such as tumor necrosis factor (TNF)-α and interleukin (IL)-1β." (PMID 31938471, 2020). "A reduction in diabetes-induced elevation of serum IL-1β, TNFα, VEGF, and Lp-LPA2 has been reported in diabetic patients in response to fenofibrate." (PMID 33396512, 2020). "In this study, we have demonstrated that diabetes increased the cleavage of caspase-3, probably by via up-regulation of TNF-α expression, since the levels of bax, an apoptotic marker of the intrinsic pathway, was similar to the ones founded in control animals." (PMID 32750068, 2020). "The close pathological and physiological tie between COPD and metabolic diseases is also revealed in the fact that such systemic inflammation markers as CRP, TNF-a and IL-6 would increase in diabetes and play an important role in the development of diseases." (PMID 33108241, 2020). "In our results, positive correlations of Firmicutes with pro-inflammatory IL-1β, TNF-α, IL-6, IL-17A and LPS demonstrated that both pro-inflammatory indicators and Firmicutes contributed to pathogenesis of diabetes." (PMID 32028957, 2020). "Some treatments, such as pentoxifylline and ACEi, reduced the TNF-α renal expression in mice and patients with diabetes." (PMID 32471207, 2020). "We induce endothelial cell (EC) dysfunction with high glucose and TNFα (H + T), that mimic the common stress in diabetes mellitus." (PMID 33060583, 2020). "In an alternative streptozotocin-induced diabetes model, elevated levels of GSK3β were accompanied with increased TNF, IL-1β, and IL-6 levels in the hippocampus." (PMID 32231133, 2020). "To investigate the role of Ufm1 in diabetes mice, we first analyzed the expression of Ufm1 and proinflammation cytokines (TNF-α, IL-6, and IL-1β) in db/db mice." (PMID 31829413, 2020).